TNF (tumor necrosis factor)
Diseases named in the same sentence as TNF in open-access papers (continued):
Sharing a sentence is not in itself a finding about the gene and the disease.
coronary artery disease (continued). "Studies have shown that TNF-a and TNF-a receptor polymorphisms have been linked to CAD and ischemic heart disease." (PMID 40218291, 2025). "Research indicates that an increase in DII scores correlates with elevated levels of interleukin-6 (IL-6), tumor necrosis factor-alpha (TNF-α), and C-reactive protein (CRP), as well as an increased risk of coronary heart disease development." (PMID 39796599, 2025). "Among these markers, both CRP and tumor necrosis factor-alpha (TNF-α) have been identified as important indicators of cardiovascular mortality, including in cases of coronary artery disease." (PMID 40649724, 2025). "Along with the degree of coronary artery disease, a significant increase in the transcriptional activity of the TNF-α gene was observed in the patients of the study group." (PMID 39684812, 2024). "For instance, there is still insufficient information regarding the impact of TNF on vascular damage in individuals diagnosed with coronary artery disease at a young age." (PMID 38541966, 2024). "In CAD (Coronary Artery Disease)-diagnosed patients TNFα is highly correlated (r2 = 0.84, p = 0.0001) with IL8 release but not with IL-1ß." (PMID 38216681, 2024). "Our study demonstrated a significantly higher transcriptional activity of the TNF-α gene in the group of patients with acute coronary syndrome and multivessel disease compared to patients with stable multivessel coronary disease." (PMID 39684812, 2024). "The analysis of the obtained results showed a significant increase in the transcriptional activity of the TNF-α gene with the severity of coronary artery disease, accompanied by a decrease in the activity of its receptor genes." (PMID 39684812, 2024). "Coronary artery disease is associated with increased levels of proinflammatory cytokines such as IL-1β, IL-6, interferon-γ (IFN-γ), and TNF-α." (PMID 38267838, 2024). "In a sample of stable and unstable coronary patients, TNF-alpha was significantly related to the severity of coronary disease." (PMID 36622512, 2023). "Studies have found that the expression level of has-miR-296-a was positively correlated with the serum levels of IL-6 and TNF-α, which were increased in patients with coronary heart disease." (PMID 37491214, 2023). "Lutein is swallowed by blood mononuclear cells and it is capable to inhibit both gene expression and secretion of IL-6, IL-1β, and tumor necrosis factor (TNF) in stable coronary artery disease patients." (PMID 37655002, 2023). "An early study also demonstrated that the expressions of TNF-α and soluble TNFRs are consistently produced in dilated cardiomyopathy and ischemic heart disease." (PMID 36012347, 2022). "The high levels of TNF-α were closely related to the formation of atherosclerotic lesions and coronary heart disease." (PMID 35425840, 2022). "A previous study suggested that in coronary artery disease individuals, the use of cholesterol-lowering drugs can significantly upregulate thrombomodulin gene expression, whereas TNF-α and NF-κB were significantly downregulated." (PMID 36012347, 2022). "Experimental studies during the past decades have established the role of inflammatory cytokines in coronary artery disease, namely interleukins (ILs), tumor necrosis factor (TNF)-α, interferon-γ, and chemokines." (PMID 36555579, 2022). "Downregulation of this miRNA was also observed in plasma of patients with coronary artery disease and was related to enhanced tumor necrosis factor (TNF)-α-induced apoptosis in endothelial cells." (PMID 35329950, 2022). "Based on the available information, it is certain that more evidence is needed in the assessment of TNF-α inhibitors in coronary artery disease." (PMID 36555579, 2022). "The activated CREB(p) binds to specific sites and regulates the expression of genes, such as B-cell lymphoma 2 and tumor necrosis factor α (TNFα), which are involved in development of ischemic heart disease." (PMID 34305645, 2021).
coronary artery disease (continued). "Background and Objectives: Tumor necrosis factor alpha (TNF-α) is proatherogenic and associated with the risk of acute ischemic events, although the mechanisms that regulate TNF-α expression in stable coronary artery disease (SCAD) are not fully understood." (PMID 34199767, 2021). "In coronary artery disease, TNF-α is expressed in atherosclerotic plaque and plays a direct role in plaque destabilization." (PMID 34988343, 2021). "Previous studies have indicated the role of TNF-α and IL-6 in cardiac remodeling, fibrosis, cardiomyocyte apoptosis and ischemic heart disease." (PMID 34046187, 2021). "It was found an important correlation between serum CTRP9 levels and adhesion molecules in coronary artery disease and T2DM patients, similarly to serum TNF-α levels in patients with coronary artery disease." (PMID 33192583, 2020). "The TNF-α was related to severe atherosclerotic plaques and played a key role in the development of coronary heart disease." (PMID 33029103, 2020). "Other research has found that for coronary artery disease patients with low IL-10/TNF-α ratio has low left ventricular ejection fraction, with high incidence of cardiac related diseases within 10 years." (PMID 32670064, 2020). "The G-308A polymorphism in the promoter region of the TNF-α gene was found to affect TNF-α protein expression and ischemic heart disease risk in, both, Caucasians and Asians." (PMID 30900134, 2020). "Numerous reports have demonstrated a close relationship between level of hs-CRP, monocyte chemoattractant protein 1 (MCP-1), interleukin-6 (IL-6), interleukin-8 (IL-8), and tumor necrosis factor (TNF)-α with pathogenesis of coronary heart disease." (PMID 32178701, 2020). "Inflammatory biomarkers (IL-6 and TNF) were shown to decrease in patients with coronary heart disease." (PMID 31316451, 2019). "Given that CVD is a major cause of mortality in T2DM, CRP has been proven to be a better predictor for coronary heart disease than other inflammatory markers, such as tumor necrosis factor alpha (TNF-α) and IL-6." (PMID 31208420, 2019). "The aim of the presented study was to determine a link between the polymorphisms (-308G>A (rs1800629) in TNFα and Pro12Ala (rs1801282) in PPARG2) and development of HF in patients with ischemic heart disease subjected to coronary artery bypass surgery (CABG)." (PMID 31275366, 2019). "The anti-inflammatory effects of testosterone were demonstrated when it reduced the expression and secretion of TNF-α and IL-1β in monocyte-derived macrophages obtained from patients with coronary heart disease." (PMID 31500378, 2019). "In that study, they showed that IL-1, IL-6, IL-6sR, and TNF-alpha expression was greater in epicardial adipose tissue than that in subcutaneous adipose tissue among patients with coronary artery disease." (PMID 30862094, 2019). "A significant relationship has also been demonstrated between circulating levels of TNF-α and severity of peripheral edema in patients with right heart failure related to ischemic heart disease or idiopathic dilated cardiomyopathy." (PMID 29875701, 2018). "Given the importance of proinflammatory cytokines in the context of the failing heart, the prevalence of Tumor Necrosis Factor-α (TNF-α), Interleukin (IL)-6 polymorphisms in patients with CHF was studied due to ischemic heart disease." (PMID 29849987, 2018). "Of interest, STAT3 is required for Flt3-dependent formation of DCs from bone marrow derived cells, and plays an important role in production of IL-1β, IL-6, and TNFα in macrophages of humans with coronary artery disease." (PMID 29800237, 2018). "Hearts were exposed to 100 pg/ml TNFα, similar to concentrations previously reported in cardiac tissue during diseases like end-stage dilated cardiomyopathy and ischemic heart disease." (PMID 28588504, 2017).
coronary artery disease (continued). "A recent large meta-analysis assessed the association between coronary heart disease risk and several other pro-inflammatory cytokines, including IL-18, matrix metalloproteinase-9, soluble CD40 ligand and tumour necrosis factor-α (TNF-α)." (PMID 28477314, 2017). "Therapeutic blockage of TNF-α in murine model prevents the development of coronary artery disease, and has been used as an alternative therapy for children with IVIG-resistance in KD." (PMID 27171184, 2016). "The activated CREBP then binds to specific sites and regulates the expression of certain genes, such as B-cell lymphoma 2 and tumor necrosis factor α (TNFα), which are involved in development of ischemic heart disease." (PMID 27190998, 2016). "We determined that the down-regulation of miR-19b level among patients with coronary artery disease was consistent with miRNA expression changes in endothelial cells following 24 h of TNF-α treatment." (PMID 26459935, 2015). "A low dose of oxLDL (8 μg/ml), below the threshold for the clinical presentation of coronary artery disease, was sufficient to activate both macrophages and mast cells and synergistically increase monocyte-endothelium adhesion via released TNF-α and histamine." (PMID 25811595, 2015). "IL-1, interferon gamma (IFN-γ) and tumor necrosis factor alpha (TNF-α) are also important both the development of coronary heart disease and plaque destabilization." (PMID 26100072, 2015). "Previous studies have demonstrated that a number of inflammatory factors are involved in the course of coronary heart disease, such as IL, TNF-α and ICAM-1." (PMID 24396397, 2014). "Recently, another study showed that PPARγ gene C161→T substitution was associated with reduced risk of coronary artery disease through modulation of pro-inflammatory cytokines, MMP-9 and TNF-α expression in a Chinese population." (PMID 20334678, 2010). "This study was designed to explore the possible association between LVDD and proinflammation reflected by IL-6 and TNF-α levels in subjects with stable coronary artery disease." (PMID 19909503, 2009). "Likewise, supplementation with flaxseed oil, a source of linolenic acid, significantly improved the expression levels of IL-1 and TNF-α in patients with diabetes and coronary artery disease." (PMID 41141350, 2025). "In this study, the transcriptional activity of the tumor necrosis factor alpha genes and their receptors was also assessed in the studied group of patients with stable coronary artery disease and acute coronary syndrome, taking into account the left ventricular ejection fraction." (PMID 39684812, 2024). "Considering the hemodynamically significant stenoses in coronary angiography, the analysis showed the significantly higher transcriptional activity of the TNF-α gene in the group with acute coronary syndrome and multivessel disease compared to patients with stable multivessel coronary disease." (PMID 39684812, 2024). "Yet, no baseline association between rs1800629 and TNFα serum levels was observed in Slovenian patients with coronary artery disease suggesting a need for more research to clarify this relationship." (PMID 39055623, 2024). "Recently, IL-36 has aroused great interest because of its dysregulation in inflammatory diseases, in fact the serum levels of IL-36 were found to be significantly higher with coronary artery disease, correlated with TNF-α, IL-6 and IL-32 levels and coronary artery stenosis." (PMID 38961336, 2024). "For instance, inflammatory cytokines IL-6 and TNF-α could be the main targets of miR-296a, and their expression was abnormal in peripheral blood mononuclear cell of patients with coronary artery disease." (PMID 37507655, 2023). "Fourth, since medications (e.g., anti-TNF agents) may decrease inflammatory burden and thereby the risk of CVD (e.g., ischemic heart disease), future studies are warranted to understand how specific IBD medications could influence incidence of arrhythmias." (PMID 37856566, 2023).
coronary artery disease (continued). "Several different pro-inflammatory cytokines such as IL-6, matrix metalloproteinase-9 (MMP-9), and tumor necrosis factor-α (TNF-α) are each associated with coronary heart disease risk independent of conventional risk factors." (PMID 33479786, 2021). "Likewise, patients treated surgically or with thiopurines and TNF alpha inhibitors tended to have reduced incidence rate ratio for ischemic heart disease." (PMID 33924727, 2021). "The accumulation of cardiac fat is also associated with higher levels of pro-inflammatory cytokines such as IL-6, IL-1, TNF-α, and the expression of adipokine fatty acid-binding protein 4 (FABP4) that are associated with the development of MetS and the extent of coronary artery disease." (PMID 33752666, 2021). "SDF-1α has the anti-inflammatory effect of TNF-α and plays a key role in coronary heart disease." (PMID 33936387, 2021). "Our study did not reveal any correlation between the PPARG2 Pro12Ala and TNFα -308G>A polymorphisms and development of HF in patients with ischemic heart disease after coronary bypass grafting." (PMID 31275366, 2019). "Importantly, a recent study reported lower expression of miR-10a and simultaneous higher expression of IL-6 and TNF-α in peripheral blood mononuclear cells (PBMCs) of patients with coronary artery disease (CAD) compared to control subjects." (PMID 30013975, 2018). "For example, a-linolenic acid (18:3(n-3)), extracted from a specific nut was inversely associated with CRP, IL-6, soluble tumor necrosis factor (TNF) receptors 1 and 2 and fibrinogen levels in healthy individuals and/or patients with stable coronary artery disease." (PMID 30131846, 2018). "Meanwhile, TNF-α antagonists seem to be a potential risk for ischemic heart disease although no statistical significance was reached." (PMID 30537997, 2018). "Meta-analyses suggest that the prospective risk of incident coronary heart disease (CHD) is increased in individuals with an anxiety disorder, including phobic anxiety, as well as in those with elevated levels of inflammatory measures, including CRP and TNF-α." (PMID 25875094, 2015). "Acute exercise induces a transient inflammatory response through the increase in several cytokines such as interleukin-6, tumor necrosis factor-α, C-reactive protein, and nuclear factor kappa B and oxidative stress in healthy subjects and in subjects with coronary artery disease." (PMID 26557715, 2015). "Previous research reported that the expression of hsa-miR-320a was related to an increase in inflammatory cytokines such as IL-6, MCP-1, or TNF-α, and may inhibit human-derived endothelium cell proliferation and induce apoptosis that may promote atherogenesis in coronary artery disease." (PMID 37298699, 2023). "Interestingly, testosterone replacement therapy can reduce circulating levels of inflammatory mediators, including interleukin (IL)-1β and tumor necrosis factor α (TNF-α), as well as total cholesterol in patients with simultaneous coronary artery disease and testosterone deficiency." (PMID 32499759, 2020). "In addition to elevation of the proinflammatory cytokines IL1β, TNF-α and IL-6, exercise may reduce C-reactive proteins in patients with coronary arteriosclerosis and Type II T helper cytokines (IL-5 and IL-13) in asthmatic BALB/c mice." (PMID 32778140, 2020). "Transforming growth factor-β1 (TGF-β1) and tumor necrosis factor-α (TNF-α) are central regulators of vascular inflammation and remodeling in coronary artery disease." (PMID 42123531, 2026). "(TNF-α) and interferon-γ (IFN-γ) are proinflammatory cytokines that play an essential role in developing chronic inflammatory illnesses such as coronary artery disease (CAD)." (PMID 38525188, 2024). "Rationale: We recently demonstrated that patients with coronary artery disease (CAD) and obstructive sleep apnea (OSA) carrying the tumor necrosis factor-alpha (TNF-α) A allele had increased circulating TNF-α levels compared with the ones carrying the TNF-α G allele." (PMID 37629366, 2023).
coronary artery disease (continued). "Based on the findings of the present study, the levels of SAH, IL-1β, Hcy, TNF-α and BDNF can predict the severity of coronary heart disease." (PMID 35282820, 2022). "Based on this, this study aimed to explore the expression of serum SAH, IL-1β, Hcy, TNF-α, BDNF in coronary heart disease and the relationship with the degree of coronary artery disease." (PMID 35282820, 2022). "In the diabetic animals, we observed increased TNF-α and IL-6 levels, and these alterations were improved with TMZ administration, which is coherent with a previous study in patients with stable coronary artery disease." (PMID 33680027, 2020). "After adjusting for gender, smoking, and coronary heart disease, there were significant correlations between intracranial arteriosclerosis and plasma ANP, PAI-1, TNF-α and IL-6 levels." (PMID 32548044, 2020). "In conclusion, our study suggests that miR-125b-mediated inhibition of the TNF-α/NF-κB pathway is crucial for the protection of EPCs in the inflammatory environment and may be a novel therapeutic target for enhancing the effectiveness of cell therapy for ischemic heart disease." (PMID 33005452, 2020). "In this study, we detected the serum MIAT concentration in 102 patients with coronary heart disease and 89 healthy subjects by QRT-PCR and detected the concentrations of IL-6 and TNF-α in peripheral blood by ELISA." (PMID 31143478, 2019). "The aim in this study was to investigate the effect of vitamin D (25(OH)D3) supplementation on heat shock protein 60 (HSP 60) and other inflammatory markers (IL-17, TNF-α, PAB) in patients with coronary heart disease (CHD)." (PMID 30093913, 2018). "Patients with coronary artery disease show increased expression of the proinflammatory molecules MCP-1, IL-6, IL-1β and tumor necrosis factor α (TNF-α), all of which are secreted by senescent cells through the SASP." (PMID 30597847, 2018). "In one study, this adipocyte-derived secretory protein inhibited TNFα-induced expression of ICAM-1 and VCAM-1, and its circulating levels were lower in patients with coronary disease." (PMID 27459718, 2016). "Plasma levels of tumor necrosis factor-α (TNF-α), interleukin-1β (IL-1β), and IL-6 are increased in patients with HTN and coronary artery disease." (PMID 23580870, 2013). "Specifically, patient age, gender, ischemic vs. non-ischemic heart disease, LVEF, IL-6 and TNF-α serum levels and the need for mechanical circulatory support were tested as continuous or categorical variables, respectively." (PMID 24074138, 2013). "These were evident in a study on patients with coronary artery disease, whereby the CRP and tumor necrosis factor-α (TNF-α) concentrations were found to be significantly lowered with α-tocopherol supplementation compared to placebo." (PMID 22162676, 2012). "We sought to evaluate the relationship between proinflammatory cytokine levels (TNF-alpha, IL-6) and tissue Doppler derived indices of LVDD in patients with stable coronary artery disease." (PMID 19909503, 2009). "In a 12-week study, non-obese men and post-menopausal women with coronary heart disease were provided with 30 g/day of flaxseed: the intervention group showed lower IL-6 and TNF-α levels than the control group." (PMID 40944222, 2025). "Although in patients with coronary artery disease, IL-6 levels were associated with AFIB, but not TNFα, IL-6 levels were higher in AFIB patients than non-AFIB controls." (PMID 38256155, 2024). "Several studies assessed the transcriptional activity of TNF-α genes in coronary artery disease, but no publications were found that included the assessment of their activity at various stages of the disease, as in the case of the presented results." (PMID 39684812, 2024). "The apparent disconnect between animal models of coronary heart disease and outcomes from human studies using TNF-α inhibitors may be due to limited target specificity of TNF-α inhibitors." (PMID 37534280, 2023).